CXCR4 (C-X-C motif chemokine receptor 4)
Diseases named in the same sentence as CXCR4 in open-access papers (continued):
Sharing a sentence is not in itself a finding about the gene and the disease.
acute myeloid leukemia (continued). "CXCL12/CXCR4 signaling has also been shown to increase autophagic activity and decrease cytarabine-induced apoptosis in acute myeloid leukemia cells." (PMID 37760498, 2023). "In humans, TNFR2+ Tregs in acute myeloid leukemia (AML) patients also display higher levels of C-X-C chemokine receptor type 4 (CXCR4) expression, which is positively correlated with TNFR2 expression levels on Tregs." (PMID 35741080, 2022). "Previously, we reported that sustained degradation of BRD4 led to downregulation of CD44, MYC, and CXCR4 in acute myeloid leukemia (AML) stem cells and improved survival in a mouse model of AML." (PMID 35173274, 2022). "Over-expression of CXCR4 has been identified as a promising prognostic biomarker for gastrointestinal and acute myeloid leukemia, among many other tumor types." (PMID 35571062, 2022). "It is well known that CXCR4/CXCL12 interaction leads to acute myeloid leukemia (AML) after chemotherapy and hence the strategy of conjugating the CXCR4 antagonist on the Fe3O4@Pt composite nanozyme’s surface interferes with this axis." (PMID 35711631, 2022). "We showed a direct interaction of the uPAR 3′UTR with miR-146a, miR-335 and miR-622, resulting in the down-regulation of uPAR and CXCR4 expression in acute myeloid leukemia cell lines." (PMID 35493073, 2022). "It has been shown that either uPAR and DII–DIII-SuPAR regulate CXCR4 through FPR1, and that the expression of uPAR and CXCR4 is modulated by microRNAs (miR)s in acute myeloid leukemia cells." (PMID 35158766, 2022). "The functional crosstalk between uPAR and CXCR4 was also confirmed by showing their co-regulation through a common microRNA in acute myeloid leukemia." (PMID 35493073, 2022). "In acute myeloid leukemia, targeting CXCR4 has been proven to be one of the potential treatment methods to overcome chemotherapy resistance." (PMID 34759953, 2021). "Accumulating studies have been made to understand the association between CXC chemokine ligand-12 (CXCL12)/CXC chemokine receptor 4 (CXCR4) and acute myeloid leukemia (AML)." (PMID 34327063, 2021). "CXCR4-mediated signal-regulated autophagy can also affect the survival and drug resistance of acute myeloid leukemia cells." (PMID 34447636, 2021). "For example, elevated levels of SDF-1/CXCL12 and CXCR4 bearing TEVs were found to be present in the peripheral blood and bone marrow plasma samples of patients with acute myelogenous leukemia (AML)." (PMID 33540535, 2021). "Further evaluations showed the applicability of [68Ga]Ga-Pentixafor PET/CT to identify patients with CXCR4-positive acute myeloid leukaemia and chronic lymphocytic leukaemia." (PMID 32019275, 2020). "In vivo, subcutaneous injections of BKT140 (a new-generation peptide CXCR4 inhibitor) significantly reduced the growth of human acute myeloid leukemia in a dose-dependent manner." (PMID 33363463, 2020). "Elevated protein expressions of CD markers such as IL2RA/CD25, CXCR4/CD184, CD34 and CD56 are associated with adverse prognosis in acute myeloid leukemia (AML)." (PMID 31171000, 2019). "A similar principal effect was observed for LAN-5 neuroblastoma and HL-60 acute myeloid leukemia cells that were included as controls with well-documented CXCR4 surface expression." (PMID 29776413, 2018). "The chemokine receptor CXCR4 mediates cell anchorage in the bone marrow (BM) microenvironment and is overexpressed in 25–30% of patients with acute myeloid leukemia (AML)." (PMID 28779088, 2017). "Both uPAR and CXCR4 are expressed in acute myeloid leukaemia (AML), with a lower expression in undifferentiated and myeloid subsets, and higher expression in myelomonocytic and promyelocytic subsets." (PMID 26082201, 2015). "Four cell lines including HL-60, NB4, THP-1 and U937 were chosen as cell models because the four cell lines are typical human acute myelocytic leukemia cell lines and highly express CXCR4 in the surface." (PMID 25312253, 2014).
acute myeloid leukemia (continued). "Many leukemic and lymphoma cells express CXCR4 on their surface, and CXCR4 expression levels have been proven to be a predictor of overall survival and relapse-free survival in patients with acute myeloid leukemia (AML)." (PMID 25167133, 2014). "For example, the inhibition of CXCR4 (a key receptor for tumor cell migration and adhesion) has been shown to overcome stromal-cell mediated drug resistance in acute myeloid leukemia and chronic lymphocytic leukaemia." (PMID 20459861, 2010). "This includes the upregulation of chemokine receptors like CXCR4, whose expression levels have been proposed of major prognostic impact in acute myeloid leukemia." (PMID 19265549, 2009). "Studies using primary acute myeloid leukaemia blasts and in vitro cell lines have further elucidated that Pim kinase inhibition using pharmacological inhibitors also downregulates CXCR4 on the cell surface, which leads to a reduction in CXCL12/CXCR4 signalling and cell migration." (PMID 39062849, 2024). "Furthermore, the CXCR4 antagonist induces the apoptosis of acute myeloid leukemia (AML) cells, and this apoptosis is mediated by the upregulation of miR-15a/miR-16-1, which results in the downregulation of the target genes cyclin D1 and Bcl-2." (PMID 35941537, 2022). "Clinically, CXCR4 expression in tumours is used to predict cancer aggressiveness, and the CXCR4 blocking ligand plerixafor successfully inhibited the progression of acute myeloid leukaemia (Aml I-a) in a clinical setting." (PMID 33562819, 2021). "In contrast, studies including hematologic malignancies where high CXCR4 expression is found, like non-Hodgkin-lymphoma, multiple myeloma, chronic lymphocytic leukaemia and acute myeloid leukaemia, depict the potential of [68Ga]Ga-Pentixafor PET/CT as a diagnostic marker for these malignancies." (PMID 32019275, 2020). "Although the mechanism underlying the upregulation of CXCR4 in HSPCs with somatic mutations remains unclear, the increased CXCR4 expression on PB HSPCs may help identify abnormal HSPCs that may transform into MDS/acute myeloid leukemia." (PMID 36051022, 2022). "For CXCR4, two trials (NCT00906945 and NCT00512252) studied the impact of CXCR4 blockage on disease inhibition in acute myeloid leukemia (AML)." (PMID 35453676, 2022). "The CXCR4 expression by flow cytometry in 122 acute myeloid leukemia (AML) patients between 2010 and 2014 was analyzed." (PMID 31518054, 2019). "In a mouse model of human acute myeloid leukemia (AML), M-E5 exhibited good physiological stability and was able to target and block CXCR4 on the surface of leukemic cells to inhibit mediated cell migration." (PMID 35893797, 2022). "Our analysis data suggested the predictive potential of CXCR as four CXCR members (CXCR3, CXCR4, CXCR5, and CXCR6) were significantly related to better clinical outcomes in HNSCC, as reported in acute myeloid leukemia." (PMID 35978426, 2022). "Interestingly, the expression of CXCR4 on Tregs has a significant positive correlation with the expression of TNFR2 in acute myeloid leukemia (AML)." (PMID 35494080, 2022). "Thus, we have examined the serum levels of these chemokines in parallel with their related cognate receptors (CXCR1, CXCR3 and CXCR4) in AML (acute myeloid leukemia) patients prior and post BMT (bone marrow transplantation) therapy." (PMID 34711015, 2021). "Importantly, the contribution of CXCR4 to skin homing and retention has been shown for Sézary cells and skin-residing acute myeloid leukemia (AML) cells in patients with cutaneous metastases." (PMID 34583709, 2021). "For example, in acute myeloid leukemia, MALAT1 regulates cells migration, proliferation and apoptosis, by releasing CXCR4 from the regulatory inhibition of hsa-miR-146." (PMID 35008626, 2021). "Reportedly, CXCR4 expression was concurrently increased with VEGF and IL-6 levels in stem cell chemoresistance of acute myeloid leukemia." (PMID 34070538, 2021).
acute myeloid leukemia (continued). "CXCR4 is best known for its role in diverse disorders such as HIV-1 infection, tumour development, and acute myeloid leukemia." (PMID 32843095, 2020). "In acute myeloid leukemia (AML), leukemic cells use the SDF-1α–CXCR4 interaction to migrate to HSC niches and become slowly-dividing and therapy-resistant leukemic stem cells (LSCs)." (PMID 32079173, 2020). "CXCR4 is overexpressed in a variety of cancers including chronic lymphocytic leukemia (CLL), acute myeloid leukemia (AML), myeloma, lymphomas, and solid tumors." (PMID 28526063, 2017). "Expression levels of CXCR4 support the concept, as this chemokine receptor is not only a migration marker, but is also involved in apoptosis of CLL and acute myeloid leukemia cells." (PMID 27029059, 2016). "In the treatment of acute myeloid leukemia (AML), interrupting the connection between leukemic cells and the tumor microenvironment by targeting the stromal-derived factor-1α/CXCR4 (SDF-1α/CXCR4) axis has become an attractive approach." (PMID 25544759, 2015). "Here we demonstrate that a novel designed peptide (E5) targeting CXCR4 inhibits CXCL12- and stroma-induced activation in multiple acute myelocytic leukemia (AML) cell lines and displays anti-AML activity." (PMID 25312253, 2014). "The involvement of mTORC1 in the downregulation of CXCR4 and inhibition of bone marrow infiltration of CAR-T cells and elimination of acute myeloid leukemia (AML) may provide a potential reason for the limited efficacy of cellular therapies in AML." (PMID 38581001, 2024). "Moreover, rapamycin pretreatments can attenuate mTORC1 activity and upregulate CXCR4, which promotes the migration and penetration abilities of EpCAM CAR T cell for eliminating acute myeloid leukemia (AML) in bone marrow." (PMID 36369033, 2022). "In acute myeloid leukemia, the dysfunction of CXCL12 by chronic hypoxia is dependent on cholesterol depletion, which interferes with the function of lipid rafts and thus the internalization of CXCR4." (PMID 33467722, 2021). "CXCR4 is detectable on neoplastic stem cells in solid tumors and in hematologic neoplasms, such as diffuse large B-cell lymphoma (DLBCL), multiple myeloma (MM), and acute myeloid leukemia (AML)." (PMID 32321944, 2020). "Also, CXCR4/SDF-1 signaling has been shown to be involved in the homing and proliferation of leukemia cells in acute myeloid leukemia (AML), chronic myeloid leukemia (CML), and other hematologic malignancies." (PMID 27630452, 2016). "In a phase 1/2 study of chemo-sensitization with MZ in relapsed or refractory acute myeloid leukemia, a decrease in CD184-12G5 binding was observed from pre-treatment to 6 hours, followed by an increase from 6 to 24 hours, indicating CXCR4 blockade by MZ in vivo." (PMID 25179788, 2014). "Thus, at least three adhesion mechanisms, CXCR4/SDF1 (CXCL12), VLA-4/VCAM-1 or fibronectin, and CD44/ligand, function in acute myeloid leukemia migration, retention, and survival." (PMID 22346731, 2012). "LncRNA UCA1 promotes acute myeloid leukemia (AML) progression by affecting the stability of METTL14 and upregulating the expression of CXCR4 and cytochrome P450 family 1 subfamily B member 1 (CYP1B1)." (PMID 38351139, 2024). "The T22-PE24 nanotoxin has already proved to be effective in targeting CXCR4+ cells in head and neck squamous cell carcinoma (HNSCC), diffuse large B-cell lymphoma cells (DLBCL), colorectal cancer (CRC), endometrial cancer (EC), and acute myelocytic leukemia (AML)." (PMID 39559553, 2024). "These nanoparticles effectively promoted tumor cell death in vitro and potent CXCR4-dependent anti-tumor effects without systemic toxicity in CXCR4+ tumor mouse models of lymphoma, colorectal, endometrial cancer, and acute myeloid leukemia." (PMID 37895165, 2023).
acute myeloid leukemia (continued). "Furthermore, pathway analysis with IPATM showed downregulation of “acute myeloid leukemia signaling”, as well as important pathways known for HSC maintenance and differentiation in Uhrf2−/− HSPCs, including “CXCR4 signaling”, “HIF-1α signaling”, and “Ephrin receptor signaling”." (PMID 37628583, 2023). "Another axis, the stromal cell-derived factor-1 (SDF-1a)/cxc motif chemokine receptor 4 (CXCR4), has been found to increase YY1 in acute myeloid leukemia (AML) cells." (PMID 37686541, 2023). "A previous study suggests that acquired up-regulation of OPN-b and c isoforms might prevent conventional chemotherapy drug (Daunorubicin, Cytarabine and Idarubicin)-induced apoptosis in acute myeloid leukemia (AML) cells by upregulating the expression of AKT, VEGF, STAT3, CXCR4, and IL-6." (PMID 34359989, 2021). "Moreover, SDF1-mediated CXCR4 activation induces resistance to chemotherapy drug Cytarabine, by downregulating microRNA let-7a and promoting transcriptional activation of Myc and BCL2-like 1 isoform 1 (BCL-xL) in acute myeloid leukemia (AML) cells." (PMID 27270649, 2016). "In acute myeloid leukemia (AML), a link has been found between PIM1 kinase activity and the surface expression and function of the CXCR4 receptor, with PIM1 expression levels correlating with CXCR4 surface expression." (PMID 29666622, 2018). "We previously demonstrated that CXCR4 is an important mediator of chemotherapy resistance in pediatric ALL and acute myeloid leukemia (AML), and that treatment with the FDA-approved CXCR4 inhibitor plerixafor could reverse stromal protection and chemotherapy resistance." (PMID 26360610, 2015). "They found that acute myeloid leukemia (AML) CD34+ cells with virtually absent CXCR4 expression were able to engraft, but the cells with high expression of CXCR4 did not." (PMID 21294880, 2011).
lymphoma (116 papers, 2006 to 2025). A malignant (clonal) proliferation of B- lymphocytes or T- lymphocytes which involves the lymph nodes, bone marrow and/or extranodal sites. "Our findings underscore the potential of combining CD19-targeted immunotherapy with CXCR4 antagonists to overcome the resistance mechanisms often associated with CXCL12–CXCR4 signaling in lymphoma cells." (PMID 40076664, 2025). "Various strategies, such as chemo-mobilization (CM) and the use of CXCR4 antagonists, have been explored to enhance mobilization efficacy in lymphoma, especially those at high risk of mobilization failure." (PMID 39091501, 2024). "The CXCL12–CXCR4 axis is known to stimulate solid tumor vascularization through the recruitment of CXCR4+ proangiogenic cells to neoangiogenic niches, and has been implicated in lymphoma progression, migration, and chemoresistance." (PMID 39594584, 2024). "We used Spearman’s rank correlations to determine associations between organ uptake and CXCR4-expressing lymphoma lesions." (PMID 37286923, 2023). "Aberrant CXCR4 activity has been implicated in lymphoma pathogenesis, disease progression, and resistance to therapies." (PMID 34363012, 2021). "Due to its role in immune cell development, mutations in CXCR4 can lead to lymphomas such as Waldenström’s macroglobulinemia or congenital WHIM-syndrome." (PMID 33804965, 2021). "Dysregulated CXCR4 expression has already been correlated with lymphoma cell survival and often associated with a worsened prognosis in lymphoma patients." (PMID 32019190, 2020). "Since mutations in the CXCR4 coding sequence frequently occur in B cell lymphomas, direct sequence analysis was performed on lymphoma samples (n = 25) and in lymphoma cells lines (n = 4)." (PMID 31554271, 2019). "CXCR4 immunohistochemistry (IHC) has been shown to be highly positive e.g. in mucosa-associated lymphoid tissue (MALT) type lymphomas and CXCR4 antagonists such as plerixafor prevent disease progression in non-Hodgkin lymphoma in vitro especially when combined with rituximab." (PMID 34307181, 2021). "However, Waldenström’s macroglobulinemia (WM) is probably the lymphoma subtype that is most closely linked to CXCR4 and its downstream signaling." (PMID 33669329, 2021). "Moreover, MYC activation in invasive lymphoma is associated with an increased expression of CXCR4." (PMID 40427609, 2025). "Other anti-CXCR4-based treatments are on the horizon, including, LY2624587, another anti-CXCR4 monoclonal antibody, which caused dose-dependent apoptosis in vitro and in vivo in human haematologic cancer cells and provided a significant survival benefit in a disseminated lymphoma model." (PMID 35008410, 2022). "Notably, MYC activation in aggressive lymphoma was associated with increased CXCR4 expression." (PMID 34363012, 2021). "Our data suggest that inhibiting CXCR4 signaling with JM#21 can synergize with CD19 mAbs to enhance lymphoma cell eradication by reducing tumor cells’ dissemination and improving ADCC." (PMID 40076664, 2025). "Case reports have described the expression of CXCL9 on lymphoma cells and its receptor CXCR3 on endothelial cells, as well as in other instances, such as CXCR4 expression on lymphoma cells and its ligand CXCL12 on the endothelium." (PMID 40723240, 2025). "Both the parental peptide and the optimized derivative disrupted CXCL12-mediated signaling, which plays a key role in lymphoma cell migration and survival, especially in CXCR4-expressing malignant B cells." (PMID 40076664, 2025). "In POD24‐FLs, weak CXCR3 and CXCR4 expression was found in 13.33% and 40% of lymphoma cells, with moderate CCR3 and CXCR5, and strong CCR7 in 50%, 70%, and 50%, respectively." (PMID 40896244, 2025). "In non‐POD24‐FLs, weak CCR3, CXCR3, and CXCR4 expression was observed in 50%, 11.8%, and 40% of lymphoma cells, respectively, while moderate CXCR5 and strong CCR7 expression was detected in 68.3% and 50%." (PMID 40896244, 2025).